U3 (Small nucleolar RNA U3 )
Synonyms: LOC124904382
Gene: Small nucleolar RNA gene on chromosome 18 (56,957,270 to 56,957,469, forward strand). Ensembl gene ENSG00000212539.
Gene Ontology:
Biological process: RNA processing
Cellular component: nucleolus
Homologues: Orthologues: chimpanzee U3 (99% identical), macaque U3 (70% identical). Paralogues in human: SNORD3P1 (84% identical), U3 (78% identical), SNORD3E (78% identical), U3 (77% identical), U3 (76% identical), U3 (74% identical), SNORD3G (73% identical), U3 (73% identical), SNORD3D (72% identical), U3 (72% identical), U3 (70% identical), U3 (69% identical), and 12 more.